BDNF (brain derived neurotrophic factor)
Diseases named in the same sentence as BDNF in open-access papers (continued):
Sharing a sentence is not in itself a finding about the gene and the disease.
diabetic neuropathy (17 papers, 2013 to 2025). A chronic, pathological complication associated with diabetes mellitus, where nerve damages are incurred due to diabetic microvascular injury involving small blood vessels that supply these nerves, resulting in peripheral and/or autonomic nerve dysfunction. "In future designs of exosomes, engineered exosomes loaded with neurotrophic factors (e.g. BDNF), could be targeted for diabetic neuropathy (e.g. sensory loss) to simultaneously promote nerve axon regeneration and vascular network reconstruction." (PMID 40837703, 2025). "However, prospective studies are required to define a ‘normal’ reference range for BDNF, to investigate whether early BDNF monitoring can predict the onset of diabetic neuropathy, and to determine whether interventions that increase BDNF reduce the risk of complications." (PMID 41142318, 2025). "Peripheral measurements of brain-derived neurotrophic factor and tropomyosin receptor kinase B provide the bases to study pathogenesis of neuropathic pain in diabetic polyneuropathy, and their action as biomarkers of the disease." (PMID 34586159, 2021). "The serum levels of tropomyosin receptor kinase receptor B and brain-derived neurotrophic factor in patients with diabetic polyneuropathy are significantly higher than healthy controls (p=0.000)." (PMID 34586159, 2021). "We examined 70 patients with diabetic polyneuropathy with confirming peripheral nerve dysfunction by electroneuromyography and measuring of serum levels tropomyosin receptor kinase receptor B and brain-derived neurotrophic factor by enzyme immunoassay." (PMID 34586159, 2021). "The neurotrophins nerve growth factor (NGF) and brain-derived neurotrophic factor (BDNF) have been studied in diabetic neuropathy and chemotherapy-induced peripheral neuropathy (CIPN), with higher levels postulated to have a neuroprotective effect." (PMID 34661878, 2021). "Brain-derived neurotrophic factor (BDNF) exerts beneficial effects not only on diabetic neuropathies but also on cardiovascular injury." (PMID 28178976, 2017). "The BDNF/TrkB pathway might play a critical role in the prevention of diabetic neuropathy complications." (PMID 35743182, 2022). "One of the most interesting messengers downstream of REST is brain-derived neurotrophic factor (BDNF), which has an established sensitizing role; in a diabetic neuropathy model, pre-emptive anti-BDNF treatment can reverse the IA reduction in myelinated neurons." (PMID 24461875, 2014). "In Alzheimer’s models, Brain-Derived Neurotrophic Factor (BDNF) enhances ATF6-mediated adaptive UPR, while, in diabetic neuropathy, Glial Cell Line-Derived Neurotrophic Factor (GDNF) suppresses PERK hyperactivation." (PMID 40722704, 2025). "In diabetic polyneuropathy recombinant human (rh) NGF, BDNF and NT3 have had limited benefits." (PMID 36362354, 2022). "In our study, we found that the mean level of NGF and BDNF of diabetic neuropathy animals decreased significantly (p < 0.05) compared to normal animals, while the treatment of NR showed the regeneration potential of NGF and BDNF in a dose-dependent manner." (PMID 36556476, 2022). "Therefore, like BDNF, blockage of the HMGB1/RAGE/NF-κB signaling pathway might represent a novel therapeutic strategy in the treatment of diabetic neuropathy." (PMID 31165005, 2019).
hypothyroidism (17 papers, 2012 to 2025). Abnormally low levels of thyroid hormone. "Shafiee found that the reduction of BDNF in the hippocampus is associated with impaired spatial learning and working memory of offspring born to mothers with pregnancy-induced hypothyroidism." (PMID 39839860, 2024). "Taken together, these findings suggest that the decrease in hippocampal BDNF associated with hypothyroidism is a key factor underlying the cognitive and behavioral impairments observed in this condition." (PMID 38988101, 2024). "On the one hand, spatial navigation deficits have been associated with hypothyroidism, likely stemming from reduced levels of BDNF and an imbalance in the brain's oxidants and antioxidants system." (PMID 38988101, 2024). "In a developmental hypothyroid rat model, hypothyroidism induced neuronal loss by the downregulation of BDNF survival signaling, increasing truncation of the p75 neurotrophin receptor." (PMID 38130289, 2023). "The subclinical hypothyroidism animal model exhibits spatial memory loss through BDNF TrkA/p75NTR signaling pathway." (PMID 35328405, 2022). "Lithium treatment restored TSH and GH levels, and reduced the injury-induced BDNF increase, indicating that the injury to the hypothalamus–pituitary axis was ameliorated, thereby reducing the risk of developing hypothyroidism and GH deficiency." (PMID 28415806, 2017). "Hypothyroidism is associated with decreased BDNF levels in the hippocampus, which may contribute to the cognitive and behavioral deficits observed in this condition." (PMID 38988101, 2024). "Studies have suggested that cognitive dysfunction caused by hypothyroidism may be related to the down-regulation of Brain-derived Neurotrophic Factor (BDNF)." (PMID 35869475, 2022). "Our results, along with studies in a rat model of hypothyroidism, indicate that the abnormal dendrite arborization in animals may be, at least in part, caused by the decreased expression of BDNF." (PMID 33708176, 2021). "Notably, thyroid deficiency reduces BDNF expression, suggesting a link between thyroid and BDNF." (PMID 40538625, 2025). "PM exposure can disrupt thyroid hormone signaling, leading to hypothyroidism, reduced brain-derived neurotrophic factor (BDNF) levels, and the dysregulation of GABAergic interneuron function." (PMID 40137534, 2025). "Abdelhaffez observed a decrease in BDNF levels in the offspring of rats with Methimazole induced pregnancy-induced hypothyroidism." (PMID 39839860, 2024). "This is consistent with previous research indicating that hypothyroidism can disrupt BDNF‐mediated pathways and synaptic plasticity, leading to cognitive and emotional impairments." (PMID 38988101, 2024). "For instance, recently, we found that PTU‐induced hypothyroidism reduces BDNF levels in the hippocampus and impairs spatial learning and memory in rat pups." (PMID 38988101, 2024). "Although many studies have found a close relationship between thyroid function and BDNF, previous research has mainly focused on patients with pregnancy-induced hypothyroidism." (PMID 39839860, 2024). "It regulates the neural transmission across both excitatory correlating levels of BDNF and cognition in patients with hypothyroidism inhibitory synapses." (PMID 35506116, 2022). "Maternal hypothyroidism affects the expression of fetal and newborn brain-derived neurotrophic factor (BDNF) and neuroendocrine-specific protein (NSP)-A, both of which are important mediators of thyroid hormone and have essential roles in brain development." (PMID 36337629, 2022). "Other studies have found that hypothyroidism leads to the decreased expression of brain-derived neurotrophic factor (BDNF) as a neurotrophic factor in the hippocampal brain regions." (PMID 35328405, 2022). "More human studies to correlate the levels and expression of BDNF in hypothyroidism are suggested to address this research gap." (PMID 35506116, 2022).
hypothyroidism (continued). "Various animal studies have documented reduced expression of BDNF in severe hypothyroidism, especially in offspring of rats that were treated with propylthiouracil (PTU) during pregnancy." (PMID 35506116, 2022). "Very few human studies are available correlating levels of BDNF and cognition in patients with hypothyroidism." (PMID 35506116, 2022). "Maternal hypothyroidism affects the expression of foetal and neonatal brain-derived neurotrophic factor (BDNF) and neuroendocrine-specific protein (NSP)-A, both of which are important mediators of thyroid hormone and have essential roles in brain development." (PMID 23043431, 2012). "Therefore, it is necessary to conduct more research to explore the relationship between pregnancy-induced hypothyroidism and BDNF, and the neurodevelopment of offspring, especially in clinical research." (PMID 39839860, 2024). "The PTU‐induced experimental model of hypothyroidism decreased hippocampal BDNF levels in rats." (PMID 38988101, 2024). "Animal models have shown that rats with early-onset hypothyroidism have low BDNF levels." (PMID 38130289, 2023). "Human studies depicting the effect of hypothyroidism on BDNF expression are very rare." (PMID 35506116, 2022). "Likewise, thyroxin is important for BDNF-induced survival of injured neurons, and early hypothyroidism prevents upregulation of KCC2 expression from P10 to P15 in Wistar rats." (PMID 26388734, 2015). "Our previous studies reported that maternal subclinical hypothyroidism decreased BDNF expression in rat pup hippocampi and impaired spatial learning; pups required more time during the Morris water maze test to find the hidden platform, compared with pups from NI mothers." (PMID 23043431, 2012). "By detecting the expression of BDNF mRNA and protein in the brain tissue of each group of rats (and B P< 0.01), we found that PTU-induced hypothyroidism rats express less BDNF in the brain tissue (P < 0.01)." (PMID 35869475, 2022). "In experimental models in rats with severe prenatal hypothyroidism, pups (but not parents) exhibited reduced levels of BDNF in the hippocampal tissue." (PMID 38130289, 2023). "Considering the role of BDNF in hypothyroidism, we speculate that DMF may play a role in hypothyroidism by affecting the expression of BDNF." (PMID 35869475, 2022). "BDNF and VEGF are important factors in synaptic plasticity and their reduction may contribute to the inhibition of the effects of exercise on LTP and the adverse neurodevelopmental effects in hypothyroidism during pregnancy." (PMID 31031899, 2019).
neurotoxicity (17 papers, 2012 to 2025). Toxicity that causes injury to the central or peripheral nervous system or damages its function. "Neurotoxicity may arise from the downregulation of BDNF-TrkB signaling or the upregulation of proBDNF/p75NTR, yet the underlying mechanism remains unclear." (PMID 40430064, 2025). "Neurotoxicity may also derive from phthalates-induced ROS production and down-regulation, in hippocampus, of brain-derived neurotrophic factor (BDNF), a key player in dendrite outgrowth and synaptic plasticity associated to cognitive and learning functions." (PMID 32764471, 2020).
chondrosarcoma (16 papers, 2013 to 2025). A malignant cartilaginous matrix-producing mesenchymal neoplasm arising from the bone and soft tissue. "Several lines of evidence in this study demonstrated that the expression of BDNF was associated with a metastatic phenotype of chondrosarcoma cells." (PMID 23892595, 2013). "Therefore, BDNF expression is associated with an invasive and metastatic phenotype in chondrosarcoma cells." (PMID 23874483, 2013). "Therefore, BDNF expression is associated with a metastatic phenotype in chondrosarcoma cells." (PMID 23874483, 2013). "Furthermore, the discovery of the BDNF-mediated signaling pathway helps to increase understanding of the mechanism underlying human chondrosarcoma metastasis, which could lead to development of effective therapy in the future." (PMID 23892595, 2013). "First, the BDNF/TrkB axis facilitates integrin-dependent chondrosarcoma migration via PI3K, Akt, and NF-κB signaling." (PMID 38993553, 2024). "Neurotrophic factors such as NGF and BDNF are known to play roles in tumor angiogenesis in various cancers, including breast cancer and chondrosarcoma." (PMID 38375479, 2024). "In chondrosarcoma patients, the expression of BDNF and VEGF proteins is significantly higher and correlated with tumor stage." (PMID 38375479, 2024). "For BDNF signalling, integrin β3 and β5 has already been proved to be up‐regulated and participate in manipulating endothelial and chondrosarcoma cells migration, respectively." (PMID 32803867, 2020). "We also found that CM from BDNF-treated chondrosarcoma cells markedly enhanced LEC migration and tube formation." (PMID 28771226, 2017). "Brain-derived neurotrophic factor (BDNF) is known to promote metastasis in human chondrosarcoma cells." (PMID 28771226, 2017). "Further analyses identified that BDNF promoted tumor lymphangiogenesis by downregulating miR-624-3p in human chondrosarcoma tissues." (PMID 28771226, 2017). "Our findings imply that BDNF enhances VEGF-C expression by suppressing miR-624-3p in chondrosarcoma patients." (PMID 28771226, 2017). "In order to confirm the clinical significance of BDNF in chondrosarcoma lymphangiogenesis, we performed RT-qPCR analysis to compare the expression profiles of BDNF and VEGF-C between normal cartilage and chondrosarcoma tissue." (PMID 28771226, 2017). "We found that an mTOR inhibitor (rapamycin) and siRNA both abolished BDNF-induced VEGF-C expression in chondrosarcoma cells." (PMID 28771226, 2017). "Though PI3/Akt signalling pathway can be activated by TNF-α in human smooth muscle cells or IL-1β in rat brain astrocytes, our results are consistent with BDNF-induced migration in human chondrosarcoma through a transducing signal involving TrkB." (PMID 25418464, 2014). "We therefore examined the expression of BDNF in human chondrosarcoma patients by using immunohistochemistry and western blotting." (PMID 23874483, 2013). "Our data demonstrate the importance of BDNF in the metastasis of chondrosarcoma, and suggest the use of BDNF as a novel therapeutic target for the clinical treatment of chondrosarcoma." (PMID 23874483, 2013). "To further confirm BDNF-mediated cell migration in human chondrosarcoma cells, we selected JJ012 sublines that showed higher cell mobility (see Experimental Section)." (PMID 23892595, 2013). "On the other hand, BDNF induced chondrosarcoma metastasis also through ASK1-dependent JNK/p38 pathway." (PMID 24205072, 2013). "Using western blotting and immunohistochemical analysis, we found that expression of BDNF in human chondrosarcoma tissues was significantly higher than in primary chondrocytes and normal cartilage." (PMID 23874483, 2013). "The experimental results indicate that BDNF promotes migratory ability through the up-regulation of β5 integrin in human chondrosarcoma cells." (PMID 23874483, 2013). "We found that BDNF protein expression was higher in chondrosarcoma cells (JJ012 and SW1353) than in normal chondrocytes." (PMID 23892595, 2013).
chondrosarcoma (continued). "Our results indicate that BDNF enhances the migration and invasion activity of chondrosarcoma cells by increasing MMP-1 expression through a signal transduction pathway that involves the TrkB receptor, ASK1, JNK/p38, and Sp1." (PMID 23892595, 2013). "Taken together, our results indicate that BDNF enhances the migration of chondrosarcoma by increasing β5 integrin expression through a signal transduction pathway that involves the TrkB receptor, PI3K, Akt, and NF-κB." (PMID 23874483, 2013). "We also found that BDNF increased the migration and expression of β5 integrin in human chondrosarcoma cells." (PMID 23874483, 2013). "Here, we have revealed critical new insights into BDNF function and its role in chondrosarcoma metastasis." (PMID 23874483, 2013). "Here, we found that human chondrosarcoma tissues showed significant expression of BDNF, which was higher than that in normal cartilage and primary chondrocytes." (PMID 23874483, 2013). "Treatment of chondrosarcoma cells with BDNF also increased their ability to invade a Matrigel basement membrane matrix." (PMID 23874483, 2013). "Taken together, these data suggest that activation of the TrkB receptor, PI3K, and Akt are required for BDNF-induced NF-κB activation in human chondrosarcoma cells." (PMID 23874483, 2013). "Here, we found that BDNF increases migration and up-regulates β5 integrin in human chondrosarcoma cells." (PMID 23874483, 2013). "Interestingly, BDNF was also shown to regulate tumor lymphangiogenesis by modulating the expression of VEGF-C in human chondrosarcoma tissues." (PMID 38375479, 2024). "Another finding in human chondrosarcoma showed that miR-624-3p acts as negative regulator for brain-derived neurotrophic factor (BDNF), which facilitates VEGF-C production to induce lymphangiogenesis, migration, and tube formation of LECs cultured with primordial JJ012 cells." (PMID 33172072, 2020). "Besides, NGF promotes VEGF expression in neuronal superior cervical ganglia, while BDNF increases VEGF expression in human chondrosarcoma and neuroblastoma cells." (PMID 31608227, 2019). "We next examined whether miR-624-3p regulated BDNF-enhanced VEGF-C production, by transiently transfecting the miR-624-3p mimic into BDNF-treated chondrosarcoma cells." (PMID 28771226, 2017). "However, the effect of BDNF on integrin expression and migration activity in human chondrosarcoma cells is not well understood." (PMID 23874483, 2013). "However, pretreatment with an Akt inhibitor greatly reduced BDNF-induced migration and integrin expression in chondrosarcoma cells." (PMID 23874483, 2013). "BDNF thus represents a promising new target for treating chondrosarcoma metastasis." (PMID 23874483, 2013). "Indeed, several lines of evidence in the current study confirmed that MMP-1 is involved in BDNF-induced cell migration of human chondrosarcoma cells." (PMID 23892595, 2013). "BDNF expression is up-regulated in chondrosarcoma patients, and promotes cell migration." (PMID 23874483, 2013). "Second, treatment with exogenous BDNF increased the migration of chondrosarcoma cells." (PMID 23892595, 2013). "Exogenous BDNF also increased migration, wound healing, and invasion in human chondrosarcoma." (PMID 23874483, 2013). "We therefore hypothesized that integrins are involved in BDNF-induced chondrosarcoma cell migration." (PMID 23874483, 2013). "In addition, the wound-scratching assay demonstrated that BDNF increased wound healing activity in human chondrosarcoma cells." (PMID 23874483, 2013). "The results of this study show that NF-κB activation contributes to BDNF-induced migration and β5 integrin expression in human chondrosarcoma cells and that inhibitors of the NF-κB-dependent signaling pathway, including PDTC or TPCK, inhibit BDNF-induced β5 integrin expression and cancer migration." (PMID 23874483, 2013).